SOX2 (SRY-box transcription factor 2)
Diseases named in the same sentence as SOX2 in open-access papers (continued):
Sharing a sentence is not in itself a finding about the gene and the disease.
prostate carcinoma (continued). "A downregulation of Oct-4 (57%), Sox2 (47%) and Nanog (17%) in mCRPC/NEPC (PC-3M), and downregulation of Oct-4 (28%), Sox2 (61%), and Nanog (35%) in taxane-resistant mCRPC/NEPC (DUTXR) prostate cancer cell line model was observed after combination treatment." (PMID 37476073, 2023). "The genes related to the proliferation, regeneration, and differentiation of stem cells, such as Sox2, OCT3/4, SMO, and β-catenin, were highly expressed in CD44+ prostate cancer cell." (PMID 35342431, 2022). "HIF-1α enhances the expression of stem cell marker SOX2 and acute hypoxia-mediated cell invasion, while HIF-2α elevates the chronic hypoxia-mediated SOX2 and sphere formation in prostate cancer." (PMID 33472628, 2021). "In this study, we report that TMPRSS4 confers stem–like properties to prostate cancer cells, mainly through upregulation of SLUG, TWIST1, and SOX2, leading to CTC survival and thereby contributing to metastasis as well as tumorigenicity." (PMID 34809669, 2021). "Together, these findings suggest that TMPRSS4 promotes CSC features in prostate cancer through upregulation of the SLUG- and TWIST1-induced stem cell factor SOX2 beyond EMT." (PMID 34809669, 2021). "We show that Usp9x/DUB inhibitor induced apoptosis in ERG independent prostate cancer lines (DU-145, PC-3 NE-like) and NEPC cell line (H660) through the down regulation of SOX2 and also impedes the formation of colonies in 3D-culture." (PMID 33613844, 2021). "c-Myc, along with other stem cell genes including SOX2, BMI1 and OCT-4, is highly expressed in prostate cancer stem/progenitor cells." (PMID 34094902, 2021). "Among the isolated populations from primary prostate cancers, only CD44+ CD133+ cells display in vitro self-renewal and express core stem cell genes OCT4, NANOG, SOX2, nestin, and c-kit." (PMID 31878027, 2019). "(OCT4, 19%; SOX2, 29%; NANOG, 14%; LIN28A, 9%; KLF4, 29%); the SOX2 and KLF4 genes were amplified predominantly in prostate cancer." (PMID 30287838, 2018). "Prostate cancer cells with an EMT phenotype induced by PDGFD displayed CSC features, including increased expression of SOX2, NANOG, OCT4, and Notch-1, and enhanced sphere-forming ability and rapid tumor growth in vivo." (PMID 30227608, 2018). "Previous studies also found that the embryonic markers SOX2, NANOG, and OCT4 were elevated in CSCs isolated from human prostate cancer tissue, human prostate tumor models, and some prostate cancer cell lines." (PMID 30558236, 2018). "For example, the overexpressions of YY1, SOX2 and OCT4 in prostate cancer cell lines have been reported." (PMID 27225481, 2016). "In prostate cancer stem cells, the activation of EGFR signaling increased SOX2 expression and the self-renewal capacity." (PMID 25114775, 2014). "Our analysis of 22Rv1 stem/progenitor cell marker gene expression revealed a small increase in NANOG and reduction in SOX2 in GSK-3α-silenced cells, inconsistent with selection for prostate cancer stem/progenitor-like cells." (PMID 25327559, 2014). "The involvement of SOX2 and OCT3/4 in prostate metastasis was demonstrated by targeted knockdown of these genes, which markedly suppressed the invasion of prostate cancer cells in vitro." (PMID 24086245, 2013). "In the castration-resistant prostate cancer cell line CWR-R1, endogenous expression of Sox2 was repressed by AR signaling, and AR chromatin-IP shows that AR binds the enhancer element within the Sox2 promoter." (PMID 23326489, 2013). "Prostate cancer cells (DU-145) were transduced with lentiviral vectors FUW-M2rtTA and FUW-tetO-SOX2 to introduce a constitutively expressed reverse-tet transactivator and a SOX2 transgene under the control of a tet-responsive element, respectively." (PMID 22937156, 2012). "In addition, SOX2 interacts with CLC-3 to modulate cell cycle dynamics, thus initiating and sustaining tumorigenesis in prostate cancer." (PMID 39976818, 2025).
prostate carcinoma (continued). "Thus, SOX2 can interact with CLC-3 and regulate the cell cycle, which is essential for the initiation and maintenance of tumorigenesis in prostate cancer." (PMID 39976818, 2025). "Furthermore, SOX2 enhances EMT by down-regulating E-cadherin expression via the Wnt/β-catenin pathway, thereby facilitating the migration of prostate cancer cells." (PMID 39976818, 2025). "SOX2 expression has shown to be inverselyregulated by the lack of androgens in the context of prostate cancer therapy." (PMID 39822777, 2024). "Together, these results uncover an essential role of TRIB3/SOX2/SLC7A11 axis in palbociclib-induced ferroptosis, suggesting palbociclib a promising targeted therapy in combine with ferroptosis induction for the treatment of prostate cancer." (PMID 39362848, 2024). "SOX2 is highly expressed in NEPC and promotes lineage plasticity of prostate cancer cells." (PMID 36732329, 2023). "SOX2 is described as the stem cell marker, and it has been detected in various cancer stem cell subpopulations including lung squamous cell carcinoma, medulloblastoma or CD44-positive prostate cancer." (PMID 38132438, 2023). "Sox2 and EZH2 also play a key role in prostate cancer stem cells (PCSCs)." (PMID 35342431, 2022). "Notably, we found a strong upregulation of the neuronal transcription factor, BRN2, and the stemness transcription factor, SOX2, in TRIB2-OE enzalutamide-resistant cells, which were characterized to promote lineage plasticity in prostate cancer cells." (PMID 34973338, 2022). "Additionally, while miR-34a regulates SOX2 expression through PAI-1, its overexpression reverts EMT, which suppresses invasion in NPC and enhances docetaxel sensitivity in prostate cancer." (PMID 32586280, 2020). "The transcription factors SOX2 and SOX9 are potential drivers of invasive prostate cancer that induce EMT and stemness whereas, Wnt signaling promotes tumor microenvironment in progenitor cells in castration resistant prostate cancer (CRPC) enhancing their resistance to therapy." (PMID 31798767, 2019). "Importantly, inhibition of the WNT/β-catenin pathway in enzalutamide-sensitive prostate cancer cells resulted in Enzalutamide resistance and in the acquisition of stemness properties (including OCT4, SOX2, CD44, ALDH1A, and ABCB1)." (PMID 31366128, 2019). "In this study, we analyzed immunohistochemical expression of SOX2 and RAGE expression in benign and malignant prostatic tissue samples and investigated their correlation with Gleason Grade, Gleason Score and Grade Group of prostate cancer cases." (PMID 30806068, 2019). "For example, the antioxidant enzyme Peroxiredoxin II regulates VEGF signaling in liver CSCs by upregulating BMI1 and Sox2 through a VEGFR-2/STAT3 pathway, while VEGF and VEGF receptor neuropilin-2 signaling involved a BMI1-mediated mechanism in aggressive prostate cancer." (PMID 30002682, 2018). "Interestingly, ILs-3, 6 and 11 significantly promoted colony formation and increased the expression of SOX2, CD44 and ABCG2 in both prostate cancer cell lines." (PMID 26528857, 2015). "Several of the identified targets genes are known mediators of prostate cancer cell “stemness” and self-renewal, such as NKx3.1, BMI-1, and SOX-4; some are also embryonic stem cell (ESC) regulators, such as KLF4 and SOX2." (PMID 26046794, 2015). "For instance, in prostate cancer, SOX2 promotes tumorigenesis and decreases apoptosis by activating the EGFR/PI3K/AKT pathway, and plays a critical role in EGFR-mediated self-renewal of human prostate cancer stem-like cells." (PMID 24828201, 2014). "In consistent with our previous study in prostate cancer cells with greater stemness in response to hypoxia, both KYSE70 and KYSE450 esophagus cancer cell lines were responding to hypoxia by upregulation of the stemness factors Oct3/4 and Sox2." (PMID 23409141, 2013).
prostate carcinoma (continued). "SOX2 was selected over OCT4 due to its higher detectability in plasma, independent oncogenic role in epithelial tumors, and documented expression in colorectal, breast, and prostate cancers, making it a more relevant candidate for plasma-based screening in these malignancies." (PMID 40674376, 2025). "Of note, the lack of consensus to define NE prostate cancer could explain discrepancies between SOX2 expression and NE features assessed by histology." (PMID 35491356, 2022). "Interestingly, we found that TRIB2 downregulates the luminal markers androgen receptor and cytokeratin 8 in prostate cancer cells but upregulates the neuronal transcription factor BRN2 (Brain-2) and the stemness factor SOX2 (SRY-box 2) to induce neuroendocrine characteristics." (PMID 34973338, 2022). "In this study, we showed that TMPRSS4 upregulates SOX2 expression through the EMT-inducing transcription factors TWIST1 and SLUG, suggesting potential role for TMPRSS4/TWIST1–SLUG on acquisition of CSC traits and aggressive malignancy during prostate cancer progression." (PMID 34809669, 2021). "Among the transcription factors which play a role in prostate cancer neuroendocrine transdifferentiation, are the transcription factors able to produce induced pluripotent stem cells: the Yamanaka pluripotency factors OCT4, SOX2, KLF4 and MYC, along with NANOG." (PMID 33572108, 2021). "Our experiments establish MDA-9 as a critical regulator of stem cell phenotypes in prostate cancer that are responsible for PCSC maintenance and survival through regulation of multiple stem-regulating molecules such as NOTCH1, C-myc, STAT3, NANOG, OCT4 and SOX2." (PMID 31878027, 2019). "Also, because the chemoresistance effect of Sox2 is mediated by hyperactivation of the PI3K/Akt signaling, it appears that targeted therapy against Sox2 administered in combination with paclitaxel may be a promising therapy in chemoresistant prostate cancer." (PMID 35309116, 2022). "The expression of Sox2 in prostate cancer cells, however, does not result in changes in differentiation-specific PSA expression, an increase in CD133-positive putative cancer stem/initiating cells, or the expression of known human Embryonic Stem Cells (hESC)-associated Sox2 target genes." (PMID 23326489, 2013). "Although Sox2, EZH2, and Oct4 are not used as prostate cancer stem cell markers, more and more studies confirmed the regulatory roles of these genes in PCSC." (PMID 35342431, 2022). "It is not surprising that prostate cancers highly expressing pluripotential transcription factors, such as NANOG, OCT4, and SOX2, more rapidly develop castration resistance and are associated with a poor outcome." (PMID 31366128, 2019). "We postulate that the transition of prostate cancer from adenocarcinoma to non-adenocarcinoma and small cell carcinoma involves activation of scTF genes in the sequence of POU5F1 → LIN28A/SOX2 → NANOG with tumor cells adopting a more de-differentiated state." (PMID 31146720, 2019). "Like 5D3 and SP cells, the different non-luminal-like prostate cancer cell types showed little expression of LIN28, POU5F1, NANOG, SOX2." (PMID 21605402, 2011). "Notably, in prostate cancer cells where BRN2 is silenced and SOX2 is overexpressed, NE marker expression does not increase." (PMID 40821114, 2025). "While we show that SRRM4 overexpression inhibits cell proliferation in all cancer cell lines tested (including the prostate cancer cell line DU145), in our experiments, SRRM4 did not induce SOX2 expression, which could explain the apparent contradiction." (PMID 33621242, 2021).
prostate carcinoma (continued). "However, reliable tools for detecting and targeting SOX2/OCT4-overexpressing cells are lacking, limiting our understanding of their roles in prostate cancer initiation, progression, and therapeutic resistance." (PMID 31500347, 2019). "Notably, cells treated with 30 μg/ml of BLE extract showed a significant reduction in the expression levels of Sox2, Oct4, Nanog, CD44 and CD166, all markers known to be expressed in prostate cancer stem cells, compared to control non-treated cells." (PMID 25380390, 2014).
melanoma (164 papers, 2007 to 2026). A malignant, usually aggressive tumor composed of atypical, neoplastic melanocytes. "This combination also blocks the MAPK and STAT3/SOX2 pathways, which effectively slows or stops secondary drug-resistant melanoma cell growth and proliferation as well as causes death." (PMID 39944829, 2025). "SRY (sex determining region Y)-box 2 (SOX2) is an embryonic stem cell transcription factor that is associated with dermal invasion of melanoma cells." (PMID 35163570, 2022). "To investigate mechanisms underlying BRAFi resistance in melanoma, we initially assessed SOX2 levels in BRAF-mutant melanoma." (PMID 33613844, 2021). "Here we show that ubiquitin-specific peptidase 9, X-linked (Usp9x), a deubiquitinase (DUB) enzyme controls SOX2 levels in melanoma." (PMID 33613844, 2021). "One documented mechanism of resistance is upregulation of SOX2, a transcription factor that is essential for tumor growth and expansion, particularly in melanoma tumors with BRAF mutations." (PMID 33613844, 2021). "Previous reports indicate that SOX2 is expressed in 50% of melanomas and a minority of nevi, and is associated with dermal invasion and primary tumor thickness." (PMID 30466459, 2018). "They functionally showed that the ectopic expression of SOX2 in vitro caused enhanced self-renewal capacity in melanoma cells." (PMID 25114775, 2014). "Sex determining region Y-box 2 (SOX2) is an embryonic stem cell transcription factor which expresses in human melanoma where it is associated with dermal invasion and primary tumor thickness." (PMID 22747902, 2012). "CD24 and Sox2 have been implicated in adaptive therapy resistance in melanoma." (PMID 40754577, 2025). "In addition, long-term cultivation of melanoma cells in the acidic media causes up-regulation of CD133, SOX2, and other molecules, important for self-renewal of melanoma cells." (PMID 34680442, 2021). "For example, CDK1 was associated with tumor initiation in human melanoma via interacting with SOX2." (PMID 34950739, 2021). "Decreasing SOX2 expression in melanoma cells was associated with a shift towards glycolysis, with increased lactate production and higher expression of SLC2A1/3 (also known as GLUT1/3), and hexokinase 2, which help import glucose and catalyze glycolysis in cells." (PMID 34831420, 2021). "This could be probably due to the high levels of SOX2 in acidic melanoma cells associated with an only partial SOX2 silencing efficacy." (PMID 30466459, 2018). "Since SOX2 is a potential target of miR-625, it is reasoned that ectopic of SOX2 could rescue the biological phenotypes caused by miR-625 in malignant melanoma." (PMID 28129648, 2017). "Furthermore, it is unknown if DHT can prevent STAT3/SOX2 reactivation caused by MAPK pathway inhibitors in BRAF mutant melanoma." (PMID 39944829, 2025). "Thus, our study identifies FMOD and SOX2 cooperation as a novel regulatory mechanism that might be linked functionally to melanoma metastatic competence." (PMID 35737114, 2022). "Notably, the efficacy of this combinatorial treatment in melanoma cells is not influenced by BRAF, NRAS or NF1 mutational status, opening the possibility of using these compounds to treat melanoma expressing high levels of SOX2 and GLI1 irrespectively to their mutational status." (PMID 33958721, 2021). "In addition, the subgroup of melanoma cases with high expression of both SOX2 and GLI1 exhibited lower frequency of KRAS mutations (0.0182 vs. 0.292) and higher frequency of PTEN mutations (0.1272 vs. 0.0414), although the relevance of this finding needs further investigation." (PMID 33958721, 2021). "The expression of SOX2 in human melanomas is directly related to the tumorigenicity and self-renewal of initiator cells and melanoma stem cells." (PMID 41012776, 2025).